RPL34-DT (RPL34 divergent transcript)
Synonyms: FLJ37673; RP11-462C24.1; RPL34-AS1
Gene: Long non-coding RNA gene on chromosome 4 (108,538,190 to 108,620,518, reverse strand). Ensembl gene ENSG00000234492.
Diseases named in the same sentence as RPL34-DT in open-access papers:
RPL34-DT is named in the same sentence as 2 diseases in open-access papers, as found by Europe PMC text mining. Sharing a sentence is not in itself a finding about the gene and the disease.
RPL34-DT shares sentences with these, for which no sentence is quoted: esophageal carcinoma (1 paper); papillary thyroid carcinoma (1).